PPP6R2 (protein phosphatase 6 regulatory subunit 2)
Description:
Regulatory subunit of protein phosphatase 6 (PP6). May function as a scaffolding PP6 subunit. Involved in the PP6-mediated dephosphorylation of NFKBIE opposing its degradation in response to TNF.
Synonyms: KIAA0685; PP6R2; SAPS2; dJ579N16.1; SAP190
Tractability: PROTAC: ubiquitination databases record sites on it; its protein half-life has been measured.
Target class: Protein phosphatase regulatory subunit; Phosphatase; Enzyme; Protein Phosphatase
Gene: Protein-coding gene on chromosome 22 (50,343,300 to 50,445,090, forward strand). Ensembl gene ENSG00000100239.
Subcellular location: Cytoplasm
Subcellular location (Human Protein Atlas): Cytosol; Cytoplasmic bodies
Gene Ontology:
Molecular function: protein binding; protein phosphatase regulator activity; protein phosphatase binding
Biological process: regulation of signal transduction
Cellular component: cytosol; nucleus; cytoplasm
Genetic constraint (gnomAD): Loss-of-function variants: 62 observed, 93.58 expected, observed/expected ratio (o/e) 0.66, 90% interval 0.54 to 0.82. The upper end of that interval is the gene's LOEUF score, 0.82, which puts it in group 3 of 6, group 1 being the genes least tolerant of losing a copy. Missense variants: 1,139 observed, 1,263.7 expected, observed/expected ratio (o/e) 0.9, 90% interval 0.86 to 0.95. Synonymous variants: 525 observed, 516.34 expected, observed/expected ratio (o/e) 1.02, 90% interval 0.95 to 1.09.
Homologues: Orthologues: chimpanzee PPP6R2 (99% identical), macaque PPP6R2 (93% identical), mouse Ppp6r2 (82% identical), rat Ppp6r2 (82% identical), guinea pig PPP6R2 (82% identical), dog PPP6R2 (77% identical), pig PPP6R2 (75% identical), rabbit PPP6R2 (73% identical), tropical clawed frog ppp6r2 (63% identical), zebrafish ppp6r2a (53% identical), zebrafish ppp6r2b (47% identical), Drosophila melanogaster fmt (25% identical), and 1 more. Paralogues in human: PPP6R3 (44% identical), PPP6R1 (40% identical).
Diseases named in the same sentence as PPP6R2 in open-access papers:
PPP6R2 is named in the same sentence as 19 diseases in open-access papers, as found by Europe PMC text mining. Sharing a sentence is not in itself a finding about the gene and the disease. The quoted sentences say what the papers report.
colorectal cancer (1 paper, 2021). A primary or metastatic malignant neoplasm that affects the colon or rectum. "DSVs in SGSM2 and LHFPL3 were relevant to colorectal cancer, whereas ADAP1, DLGAP2, ERC1, and PPP6R2 were related to gynecologic cancer." (PMID 33431054, 2021).
myasthenia gravis (1 paper, 2020). Myasthenia gravis (MG) is a rare, clinically heterogeneous, autoimmune disorder of the neuromuscular junction characterized by fatigable weakness of voluntary muscles. "It was one of four susceptibility genes(PPP6R2, CANX, FAM136A,and FAM69A) (p < 0.05) in ophthalmoplegic subphenotypes of myasthenia gravis (OP-MG), showed altered expression." (PMID 32098576, 2020).
Obesity (1 paper, 2022). Accumulation of substantial excess body fat. "In addition, obesity also has an impact on the DNA methylation of the PPP6R2 gene." (PMID 35589784, 2022).
cancer (3 papers, 2016 to 2024). A tumor composed of atypical neoplastic, often pleomorphic cells that invade other tissues. "While PPP6R2 is a regulatory protein implicated in cell cycle entry and progression whose loss of function causes genomic instability, TNKS is involved in the Wnt pathway whose destabilization and deregulation led to uncontrolled proliferation and, therefore, progression of cancers." (PMID 37175550, 2023). "PPP6R2 may be a potential early biomarker for CVD and cancer." (PMID 39449424, 2024).
PPP6R2 also shares sentences with these, for which no sentence is quoted: asthma (2 papers); acute kidney injury (1); alcohol abuse (1); chronic kidney disease (1); chronic obstructive pulmonary disease (1); delirium (1); dementia (1); gynecologic cancer (1); heart failure (1); lung carcinoma (1); peritonitis (1); pneumonia (1); psychiatric diseases (1); Stroke (1); tumor (1).